GATA4 (GATA binding protein 4)
Diseases named in the same sentence as GATA4 in open-access papers (continued):
Sharing a sentence is not in itself a finding about the gene and the disease.
tumor (continued). "We interrogated the transcriptional consequences of CRISPR targeting of Gata4 by performing RNA-seq on micro-dissected tumors from sgGata4- and sgCtrl-targeted tumor-bearing mice." (PMID 35017504, 2022). "GVAX, Gata4 overexpression, and anti-PD-1 antibody together efficiently prevented detectible tumor growth." (PMID 35017504, 2022). "Transplant experiments showed that Gata4 expression restricted tumor growth and resulted in reduced tumor volume, indicating that Gata4’s tumor-suppressive effects are conserved across a variety of tumor types with varying immunogenicity." (PMID 35017504, 2022). "To develop a tractable system to study the effects of GATA4 on tumor formation, we chose to ectopically activate the GATA4-regulated secretory program by forced Gata4 expression." (PMID 35017504, 2022). "Quantitative RT-PCR (RT-qPCR) revealed that genes representing mesodermal (T, Kdr), endodermal (Foxa2, Gata4/6, Sox17) and ectodermal (Fgf5, Sox11 for primitive ectoderm) differentiation were generally activated in tumor." (PMID 33468253, 2021). "GATA4 was identified as an essential tumor suppressor and its expression was uniformly decreased in human LC cell lines compared to normal lung epithelial cell lines 16, which was consistent with the results of our study based on CCLE datasets." (PMID 34093794, 2021). "It’s reported that in pediatric AML patients, GATA4 was epigenetically inactivated by promoter hypermethylation, and acts as a tumor suppressor." (PMID 34738870, 2021). "In lung cancer, aberrant promoter DNA methylation leads to a loss of GATA4 and GATA5 activity as tumor suppressor genes." (PMID 34827720, 2021). "β-catenin was recruited by GATA4 and thereby enhanced transcription activity of GATA4 to exert tumor suppressor function." (PMID 31903133, 2020). "In order to find out by which means GATA4 exerted its tumor suppressive function, we first checked cell death of HepG2 and Huh7 in response to GATA4 expression." (PMID 31903133, 2020). "The effect of SAM to decrease methylation was proved to be beneficial in certain genes (HT-29: DTX1, GATA4, SEZ6L, TP53INP1; SW480: HAAO, TAL1), whose hypermethylation was associated with tumor progression according to the scientific literature." (PMID 32784836, 2020). "miR-126 negatively regulates insulin receptor substrate 1 (IRS-1), Kristen rat sarcoma viral oncogene (KRAS), and GATA binding protein 4 (GATA4) and its loss is implicated in tumor progression." (PMID 32906592, 2020). "Consistently, TCGA data showed significantly lower mRNA expression of GATA4 in HCC tumor nodules in comparison to para-tumoral tissues." (PMID 31903133, 2020). "Our current work therefore unveiled a previously unnoticed tumor suppressor enhancing module orchestrated by ectopically expressed GATA4 in HCC cells: 1)." (PMID 31903133, 2020). "Ectopically expressed GATA4 orchestrated the assembly of a tumor suppressor enhancing module in HCC cells by directly binding and inhibiting the transcription activity of β-catenin to transcribe canonical Wnt pathway target genes." (PMID 31903133, 2020). "Among the tumor cell lines, GATA4 protein level was relatively higher in SNU-387, SK-HEP1, NeHepLxHT and HUH-7 than in SNU-449, PLC-PRF-5 and HepG2." (PMID 31903133, 2020). "We found comparable GATA4 protein level between tumor samples and cancer cell lines, which was consistently lower than that of para-tumoral tissues." (PMID 31903133, 2020). "To evaluate its TSG function in vivo, we sought to check the tumor formation after knockout of GATA4 in hepatocytes of transgenic mouse model." (PMID 31903133, 2020). "and thereby inhibited the oncogenic function of β-catenin; 2) β-catenin enhanced transcription activity of GATA4 to exert tumor suppressor function." (PMID 31903133, 2020).
tumor (continued). "In stark contrast to control group, we detected notable lung tumor nodules in 3 out of 4 mice post 10 weeks of lenti-sgGATA4 nasal inhalation (referred to as KG mice for KrasG12D/GATA4-/-), further supporting the tumor suppressive function of GATA4 in vivo." (PMID 30971692, 2019). "GATA4, a tumour suppressor, is degraded by p62-dependent selective autophagy and is confirmed to be downregulated in GBM." (PMID 31708690, 2019). "In serval cancer types, GATA4 serves as a potential tumor suppressor, and hypermethylation and hypomethylation of GATA4 are closely related to the malignant behavior of cancers." (PMID 31192139, 2019). "GATA4 is known to be more likely to behave as a tumor suppressor gene since the increased expression levels correlate with the terminal differentiation in the intestinal epithelium and the terminal differentiation induced in CRC cells by sodium butyrate." (PMID 31405379, 2019). "GATA4 is a negative regulator of normal astrocyte proliferation and suppresses tumor cell growth through direct activation of p21." (PMID 28498815, 2017). "Epigenetic inactivation of GATA4 by promoter hypermethylation was observed in both AML cell lines and pediatric AML samples; our study implicates GATA4 as a putative tumor suppressor gene in pediatric AML." (PMID 26490736, 2015). "Except that some tumor tissues exhibited nuclear positivity of GATA4 (Fig. 2B3, T184, red arrow), majorities of intratumoral (T49&T184) and peritumoral (P184) tissues showed diffuse cytoplasmic expression pattern of GATA proteins." (PMID 24498120, 2014). "In primary GCTs, high-level expression of both HER2 and high GATA4 correlated positively to higher tumor stage (stages II–III and Ib–III, P < 0.05)." (PMID 24687970, 2014). "Recently, GATA4 and DcR1 were suggested to be a tumor suppressor genes involved in tumorigenesis in various types of human cancers." (PMID 23320456, 2013). "DNA methylation at the promoter region of the MGMT, CDKN2A, SFRP1, TMEFF2, HS3ST2 (3OST2), RASSF1A and GATA4 genes was evaluated by quantitative methylation specific PCR in both tumor and corresponding normal appearing colorectal mucosa samples." (PMID 20098741, 2010). "For control a primary tumor and the corresponding liver metastasis from stomach, a human tissue that normally expresses Gata4 was included." (PMID 19551151, 2009). "Owing to technical limitations in establishing a northern blot for GATA-4, expression levels of this gene were determined by real-time RT-PCR in a set of 73 primary tumours." (PMID 19707195, 2009). "We found by ChIP assay that the histone H3 and H4 acetylation of the GATA4 locus decreased greatly in cancer cells comparing to GATA4-positive non-tumor cells." (PMID 19649254, 2009). "A recent study identified GATA4 as a tumor suppressor that represses MMP9 transcription." (PMID 41514651, 2025). "Importantly, Sox11-dependent expression of a selection of genes from bulk RNA-seq clusters 1, 2, and 8, and of the tumor suppressor Gata5, a paralog of Gata4, had already been proven by targeted by qRT-PCR analyses, or was newly confirmed." (PMID 40393982, 2025). "This variability may indicate differential transcriptional regulation of the GATA4 gene, potentially influenced by tumor subtype, epigenetic alterations, or tumor microenvironment dynamics." (PMID 41303462, 2025). "GATA4 was expressed in 42% of tumors and decreased during tumor progression." (PMID 40699746, 2025). "We found that tumor expression of both GATA4 and GATA6 were significantly related to DFS." (PMID 36830789, 2023). "High GATA-4 was associated with a reduced DFS, independently of tumor stage." (PMID 36869369, 2023). "Finally, regarding the differences between tumor tissue and lymph node metastasis, it was observed that the expression of GATA4 was lost in 4 (12%) tumors, remained the same in 26 (74%) and became positive in 5 (14%)." (PMID 36830789, 2023).
tumor (continued). "However, other authors have described that GATA4 inhibits the proliferation of PDAC tumor cells and favors cell differentiation." (PMID 36830789, 2023). "CCL2 neutralization partially rescued Gata4’s tumor-suppressive phenotype." (PMID 35017504, 2022). "Furthermore, IRGs associated with tumor progression, including PDGFA, ITPR3, SLPI, TICAM1, and GATA4, were identified." (PMID 36588538, 2022). "Consistent with our previous mixing experiment, Gata4 induction led to decreased tumor size." (PMID 35017504, 2022). "GATA4 also acts in a distinct capacity to control a stress-inducible pro-inflammatory secretory program that is associated with senescence, a potent tumor suppression mechanism, but also operates in non-senescent contexts such as tumorigenesis." (PMID 35017504, 2022). "GATA4 is not frequently mutated but is frequently deleted in multiple human tumor types and frequently silenced in lung and gastric cancers and 61% of colon cancers." (PMID 35017504, 2022). "Infiltrating CD45+CD3+CD4+ and CD45+CD3+CD8+ T cells were more abundant in Gata4-activated tumors than controls, and the increase was dose-dependent, suggesting that there is a minimum number of Gata4-expressing cells necessary in a tumor to achieve maximal tumor suppression." (PMID 35017504, 2022). "Notably, activation of the GATA4-dependent secretory program combined with an anti-PD-1 antibody robustly abrogates tumor growth in vivo." (PMID 35017504, 2022). "In addition, the decrease of GATA4 expression with more advanced disease stage and T stage of the tumor was statistically significant (P < 0.05)." (PMID 36588538, 2022). "Moreover, studies have identified some GATA family members, specifically GATA4, GATA5, and GATA6, as tumor suppressor genes associated with several cancer diseases." (PMID 34827720, 2021). "GATA4 inhibits tumour growth by affecting the assembly of tumour suppressor enhancement modules." (PMID 34109184, 2021). "The dysregulation and aberrant expression of GATA4 has been correlated with tumor progression." (PMID 33778495, 2021). "We have functionally validated tumor suppressor function of GATA4." (PMID 31903133, 2020). "Our data suggested that by orchestrating a tumor suppressor enhancing module, ectopic expression of GATA4 in HCC cells might be a valid choice to shrink HCC tumors." (PMID 31903133, 2020). "GATA4 thus created a tumor suppressor enhancing module between GATA4 itself and β-catenin." (PMID 31903133, 2020). "Additionally, RT-PCR also indicated the gene expression of iPSC-derived tumor tissue in three germ layers, demonstrating expressions of GATA4 in endoderm; HAND1 and GATA6 in mesoderm; and TUBB3, MAP2, and GFAP in ectoderm." (PMID 33224204, 2020). "Thus, we validated a tumor suppressor enhancing module assembled by ectopically expressed GATA4 in HCC cells." (PMID 31903133, 2020). "Of note, tumor suppressive function of GATA4 was recently reported in other cancers." (PMID 31903133, 2020). "In contrast, retroviral expression of GATA4 significantly inhibited tumor formation." (PMID 30971692, 2019). "Therefore, although tantalizing, a role of the GATA4/FOG1/NuRD axis as potential tumor suppressor remains unresolved at the present time requiring increased cohorts of aged animals." (PMID 24367609, 2013). "So far, our microarray analyses suggest higher GATA-4 expression levels in more aggressive tumours." (PMID 19707195, 2009).
tumor (continued). "Additionally, GATA4 expression was significantly correlated with tumor size (p = 0.049), being more frequently overexpressed in tumors measuring less than 100 mm in maximum diameter (15 out of 20 cases with RQ > 50), compared to those exceeding 100 mm (10 out of 22 cases)." (PMID 41303462, 2025). "Given the complex regulation of gene expression, several key upregulated genes were found, including GATA4, SALL3, IL33, SOX10, and SCG3/SHC4, while the downregulation of keratin genes suggests a loss of epithelial differentiation, contributing to aggressive tumor behavior." (PMID 40647405, 2025). "Furthermore, we explore potential co-expression patterns or correlations between SOX9, GATA3, and GATA4, which may reflect shared regulatory pathways or converging roles in tumor differentiation, plasticity, or stromal remodeling." (PMID 41303462, 2025). "Moreover, GATA4 has been reported to regulate a stress-induced secretory program that recruits cytotoxic CD8+ T cells, and its loss resulted in diminished lymphocyte infiltration and reduced tumor growth in multiple model systems." (PMID 41514651, 2025). "Finally, the diagnostic and prognostic potential of four metagene signatures consisting of selected GATA4/6 target transcripts is evaluated in a multi-cancer panel of ~7000 biopsies from nineteen tumor types, revealing elevated specificity for gastrointestinal tumors." (PMID 39456519, 2024). "To determine whether CCL2 was required for Gata4-mediated tumor suppression, we transplanted KP tet-Gata4 tumor cells into immunocompetent syngeneic hosts and divided mice into control or doxycycline groups with either a CCL2-neutralizing antibody or isotype control." (PMID 35017504, 2022). "Previous studies indicated that GATA4 might act as a putative tumor suppressor gene." (PMID 36588538, 2022). "Furthermore, many of these genes are tumor suppressors, such as GATA4 and IGFBP3/5, and may contribute to the therapeutic effect of PRC2 inhibition in tumor." (PMID 35169119, 2022). "Moreover, tumor volume was inversely proportional to the percent of cells with dox-inducible Gata4." (PMID 35017504, 2022). "Thus, we speculate that the low expression or loss of activity of oncogenes such as CA8 is one of the reasons for the high expression of tumor suppressor genes such as K17, GATA4 and p16lnk4a." (PMID 33324659, 2020). "In addition, UXT also interacts with many other well-known tumor-associated transcription factors, such as NF-κB, EVI1, GATA4, FOG2, NKX2.5, and Foxp3, which suggests that UXT may regulate tumorigenesis though multiple signaling pathways." (PMID 31481081, 2019). "Downregulation of the tumor biomarkers Gata4 and Lhcgr could be a sign of regressing tumor cells." (PMID 30400009, 2019). "On the contrary, their concomitant strong expression might indicate an abnormal activation of the GATA pathway of cellular proliferation and immortalization: GATA-4 may be co-responsible of the progression of these neoplasms, though they are indolent and clinically benign." (PMID 23029311, 2012). "In addition, the SUMOylation of GATA4 at the K366 site has been shown to augment its transcriptional activity, suggesting that the SUMOylation of GATA4 could be another determinant of its tumor suppressive effect." (PMID 38653973, 2024). "In tumour xenografts, the expression of multiple characteristic SASP factors, including GATA4, MMP2/10, ITGA2 and GBP1, significantly increased after PRC2 inhibition, contributing to ECM remodelling and tumour regression." (PMID 39270064, 2024). "In addition, we verified other NF-κB downstream genes (VEGFA, TNFα, and uPA) which involved in the regulation of tumor microenvironment and found that GATA4 can also down-regulate their mRNA levels, suggesting that GATA4 may be a potential factor in the regulation of tumor microenvironment." (PMID 38653973, 2024).
tumor (continued). "In order to study the changes in the expression of GATA4 and GATA6 during the process of tumor development, their expression was studied in healthy tissue, PanIN, tumor tissue, and metastatic lymph node." (PMID 36830789, 2023). "When the differences of GATA4 and GATA6 were studied in the paired samples of PanIN and tumor tissue, it was observed that the expression of GATA4 was lost in 5 (15%) cases, remained the same in 25 (73%) and increased in 4 (12%)." (PMID 36830789, 2023). "GATA4 and GATA6 expression was studied by IHC in TMA samples of normal tissue, PanIN, tumor tissue and lymph node metastases from a series of 89 patients with resected PDAC." (PMID 36830789, 2023). "To identify factors secreted by tumor cells directly in response to Gata4 overexpression, we used cytokine arrays to assay conditioned media from tet-Gata4 and tet-GFP KP tumor cells." (PMID 35017504, 2022). "We created a 33% tet-Gata4 and 67% tet-GFP tumor cell population and transplanted the mixture subcutaneously." (PMID 35017504, 2022). "GATA4 and GATA5 tend to mark fully differentiated epithelial cells and confirmed as potential tumor suppressors, while GATA6 expresses in the immature proliferating cells in the intestinal crypts and classified as potential oncogene." (PMID 35488350, 2022). "Recent advancements in targeted reprogramming [like selective ablation of Wt1 in Ctnnb1 (cadherin-associated protein β1) over-expressing Sc results into Lc cell-like tumor development, manipulation of SF1, GATA4,etc." (PMID 36686449, 2022). "Despite aberrant promoter hypermethylation of ALDH1A2, OSR2, GATA4, and GRIA4 have already been reported in several human tumor cell lines or tumor tissues." (PMID 34745985, 2021). "GATA binding protein 4 (GATA4), a protein in the GATA family of zinc-finger transcription factors, can recognize the GATA motif, which is present in the promoter of many tumor-related genes." (PMID 33648545, 2021). "Concerning average beta values of GATA4, GRIA4, and IRX4, the patients with tumor stage IV had the highest level as compared to the subgroup patients with stage I/II/III tumor." (PMID 34745985, 2021). "A pan-cancer analysis with 10,967 tumor samples in 32 TCGA cohorts revealed that a low frequency of ALDH1A2 (1.4%), OSR2 (5%), GRIA4 (3%), GATA4 (4%), and IRX4 (5%) was genetically altered." (PMID 34745985, 2021). "Nonetheless, we decided to focus on 4 TSGs (TFPI2, SOX17, GATA4, and FBN2) because we later confirmed that these genes had a cancer-specific methylation pattern in primary OSCC tumor samples." (PMID 31405379, 2019). "Although GATA4 and DKK3 acted as tumor suppressors in most carcinomas, they promoted tumor progression in HB." (PMID 27788486, 2016). "When GATA4 and ETS1 were depleted, the tumor propagation and formation were significantly inhibited." (PMID 26625313, 2016). "Similarly, GATA factors such as GATA4 play key roles in the development of the gastrointestinal tract as well as in the development of the heart, pancreas and liver, and so these factors could play tumour-suppressor roles in many different cancer types." (PMID 27562343, 2016). "Under the addition of DMSO, T24 Mut shETS1 and T24 Mut Double sh displayed a remarkable decrease in tumor volume, which suggested that the depletion of ETS1 (31.85%, P < 0.05) and both of GATA4 and ETS1 (41.16%, P < 0.05) inhibited the growth of T24 Mut cells." (PMID 26625313, 2016). "In contrast to GATA-4, FOG-2 expression did depend on both stage of the tumour and age at diagnosis." (PMID 19707195, 2009).